LEPR (leptin receptor)
Diseases named in the same sentence as LEPR in open-access papers (continued):
Sharing a sentence is not in itself a finding about the gene and the disease.
Obesity (continued). "Rather, LepR and intracellular signaling cascades such as phosphorylation of ERK1/2 in tanycytes of the mediobasal hypothalamus and endothelial cells at the BBB seem to be principal regulators of transport leptin across brain barriers and obesity." (PMID 34066779, 2021). "Our data also suggest that leptin receptor blockade did not exacerbate obesity and obesity-induced SDB in NZO mice." (PMID 34276408, 2021). "In the context of multifactorial and polygenic obesity, LEP/LEPR heterozygosity may represent an underdiagnosed factor." (PMID 34448070, 2021). "Nevertheless, as proposed in animal studies, diet, sex, and other factors, such as age may influence development of obesity in LEP and LEPR heterozygotes." (PMID 34448070, 2021). "In conclusion, systemic leptin receptor blockade attenuates hypertension in NZO mice without exacerbating obesity and SDB." (PMID 34276408, 2021). "They reported that HFD feeding decreased hypothalamic AgRP mRNA expression in control mice, but not in mice in which the AT1R was deleted in LepR-containing neurons (the AT1R and LepR are co-expressed in the ArcN), supporting a link between AT1R and NPY suppression with obesity." (PMID 32160920, 2020). "Many genes implicated in monogenic obesity have also been flagged in these large-scale obesity GWAS, including LEPR, MC4R, and POMC, although they are usually not the most prominent findings." (PMID 33233816, 2020). "Farther, obesity is not related to the suppression of appetite nor body mass reduction, due to leptin receptor resistance." (PMID 33008429, 2020). "LepR reactivation before the onset of obesity did not affect the body weight of Ubi-LepRNull males in the long-term, but Ubi-LepRNull females still showed higher body weight than Ubi mice." (PMID 30694175, 2019). "In the current study, targeted resequencing of the coding regions of 31 selected genes known to be involved in monogenic forms of obesity (excluding LEP, LEPR and MC4R) was performed in 23 probands from Pakistani families with severe early-onset obesity segregating as an autosomal recessive trait." (PMID 31488071, 2019). "In contrast, the newly discovered variant at the LEPR/LEPROT locus associated with BMI-AP did not associate with other growth traits reported here, or in previous studies on childhood/adult BMI and obesity." (PMID 31840077, 2019). "Although studies evaluating the modulating effects of specific carbohydrate sources in the relationship between LEPR and obesity were not identified, studies reporting the interactions between different genetic variants and carbohydrate intake are available." (PMID 30126176, 2018). "We did not detect statistical associations between LEPR rs11371101, FTO rs9939609, MC4R rs2229616, and PPARG-2 rs1801282 polymorphisms and most obesity-related phenotypes and metabolic parameters." (PMID 29679223, 2018). "db/db mice in the model group showed marked glucose intolerance, but the mice treated with metformin or NGR1 were partially protected from obesity-induced glucose intolerance that arises due to the lack of a leptin receptor in this animal model." (PMID 30450046, 2018). "A study aimed at exploring the relationship between obesity and depression found that, a combination of diet induced obesity and chronic unpredictable mild stress (CUMS) resulted in increased leptin levels but a decrease in LepR expression, along with depressive behaviors." (PMID 30405455, 2018). "Consistently, mice lacking leptin (ob/ob mice) or the LEPR (db/db mice) are characterized by hyperphagia and decreased energy expenditure, resulting in severe morbid obesity." (PMID 30224299, 2018). "Expression of IGF-1 and LEPR indicates a relevant role in androgenic features reversion present in PCOS, hormonal equilibrium, body weight regulation, and glucose metabolism, therefore, under phenotype obesity and infertility regulation in this model." (PMID 29430464, 2017).
Obesity (continued). "Further, a recent study showed that WT mice with diet-induced obesity retain sensitivity to the central anorexigenic actions of endogenous leptin and gain weight when treated with a leptin receptor antagonist, unlike genetically-obese mice." (PMID 28427343, 2017). "Leptin receptor signaling cascade appears to be compromised with obesity, resulting in the lack of action of the high levels of this hormone in obese people." (PMID 28811937, 2017). "But, despite highly elevated beta cell proliferation in LepR-KO mice, acute inducible obesity did not shorten the beta cell replication refractory period." (PMID 27003683, 2016). "Previous attempts to induce acute LepR deletion using Rosa-CreERT2;LepRflox/flox mice did not result in obesity due to inadequate floxing of LepR in the brain." (PMID 27003683, 2016). "The requirement of this pathway to prevent severe hyperphagia and obesity was recently demonstrated in mice specifically lacking the STAT3-binding site of the leptin receptor and in mice with reduced level of STAT3 protein selectively in the CNS." (PMID 26904147, 2016). "The requirement of this pathway to prevent severe hyperphagia and obesity was recently demonstrated in mice specifically lacking the STAT3-binding site of the leptin receptor and in mice with reduced levels of STAT3 proteins selectively in CNS." (PMID 26904147, 2016). "The IL6, LEPR, NAMPT, and AMD1 gene variants previously found to associate among Indian children did not associate with risk of obesity or obesity-related quantitative measures among Caucasian children and juvenile men from Denmark." (PMID 26558825, 2015). "The db/db mice lacking of leptin receptor were used as an animal model of type 2 diabetes with obesity." (PMID 26234821, 2015). "The current study illustrates that four variants (IL6 rs2069845, LEPR rs1137100, NAMPT rs3801266, and AMD1 rs2796749) implicated in childhood obesity among Indians are not strongly associated with obesity among Danish children and juveniles." (PMID 26558825, 2015). "Db/db mice, possessing a natural mutation in the leptin receptor (Ob-Rb) gene, are widely used as model mice of NAFLD and obesity/diabetes; however, these mice do not spontaneously develop steatohepatitis or liver fibrosis." (PMID 24466347, 2014). "The present results show that LEP A19G, LEP G2548A; LEPR K109R and LEPR Q223R SNPs are unlikely to be a relevant obesity marker among Malaysians, at least among the Kampar suburban population, but were associated with ethnicity." (PMID 24947733, 2014). "In relation to obesity and T2DM, LEPR gene polymorphisms were not extensively studied among different populations." (PMID 24051404, 2013). "ZDF presents hyperphagia, as a result of a nonfunctioning leptin receptor, which in turn leads to obesity similar to the prediabetic state in humans." (PMID 23691518, 2013). "The lack of correlation of the tested genes and obesity in ALL survivors together with changes in leptin/soluble leptin receptor plasma levels suggest, that influence of the selected genetic polymorphisms was not very potent." (PMID 21631924, 2011). "In the majority of cases of obesity, despite both an intact leptin receptor and high circulating levels, leptin fails to bring about weight loss." (PMID 17448988, 2007). "The treatment of these two cell lines with leptin at 10 ng/mL and 100 ng/mL, concentrations that mimic plasma leptin levels in lean individuals and those with obesity, led to marked overexpression of LEPR in (the more aggressive cell line) MDA-MB-231 cells but not in MCF-7 cells." (PMID 41562922, 2026). "Notably, leptin-treated NachBac mice showed a p-STAT3 expression level comparable to that of leptin-treated ob/ob mice, demonstrating that, despite severe obesity development and phenotypic leptin resistance, leptin-induced p-STAT3 signaling remains intact in Arc LepR neurons." (PMID 40540394, 2025).
Obesity (continued). "Genes in the leptin–melanocortin pathway, such as leptin (LEP), leptin receptor (LEPR), melanocortin-4 receptor (MC4R), adenylyl cyclase 3 (ADCY3), and brain-derived neurotrophic factor (BDNF) genes, are established contributors to obesity and insulin resistance." (PMID 38674857, 2024). "Interestingly, in vitro leptin treatment did not alter the expression of Ob-Rb, the long isoform of the leptin receptor, in ASCs from obese mice, suggesting stable receptor expression despite the conditions of obesity." (PMID 39065712, 2024). "In support of this view, while obesity has been shown to increase LepR expression in the ArcN, the administration of leptin to further increase plasma levels in obese mice failed to induce additional LepR expression, unlike in lean mice." (PMID 36769012, 2023). "However, it is not approved for treating obesity in individuals not impacted by POMC, PCSK1, LEPR deficiency, or Bardet-Biedl syndrome." (PMID 37937009, 2023). "The most prominent and ubiquitous characteristic of children identified with biallelic (likely) pathogenic variants in LEP, LEPR, and MC4R genes was the onset of severe obesity and hyperphagia at a very young age—they lacked satiety and were constantly in demand of food." (PMID 37659411, 2023). "In one of the studies, the authors found a positive association of skinfold thickness (as an indicator of adiposity in neonates) with free leptin (calculated as plasma leptin/soluble leptin receptor) in women with pregestational obesity but negative in non-obese mothers." (PMID 34523036, 2022). "Consequently, pleiotropic genes like LEPR and MC4R could influence the phenotype of both obesity and precocious puberty; however, their effect on precocity puberty and its magnitude are still unknown." (PMID 35624438, 2022). "Our previous study has proven that leptin/LepR signaling, an important adipocytokine signaling, could promote osteogenesis differentiation through STAT3 signaling pathway, which indicated the intrinsic interaction between obesity and OLF." (PMID 35712246, 2022). "Nevertheless, not all obesity conditions are the result of LEPR dysfunctions." (PMID 34208585, 2021). "On the other side, fatty liver was observed in LEPR wt/- rats even in the absence of obesity." (PMID 34448070, 2021). "However, this is clearly not the full story since knockdown of leptin receptor-positive POMC neurons only leads to mild obesity." (PMID 33679451, 2021). "It is conceivable that metabolic abnormalities in LEP/LEPR heterozygosity may be secondary to overweight or obesity, irrespective of the genetic status, is conceivable." (PMID 34448070, 2021). "Notably, circulating levels of leptin were increased in HFD-fed mice compared to LFD-fed mice with no alterations in leptin receptor hypothalamic expression, suggesting no alterations in leptin sensitivity, as has been previously reported in obesity." (PMID 33349590, 2021). "Considering the physiological and clinical importance of leptin receptor (LEPR) in regulating obesity and the fact that porcine LEPR expression is not known to be controlled by lncRNAs and miRNAs, we aim to characterize this gene as a potential target of SSC-miR-323 and the lncRNA TCONS_00010987." (PMID 31480192, 2020). "We hypothesize that central adiposity (rather than general obesity, as measured by BMI) is the etiologic mechanism linking LEPR expression in the breast tumor microenvironment with aggressive tumor clinicopathology and ultimately poorer prognosis." (PMID 32046756, 2020). "Therefore, LepR reactivation was induced before the onset of obesity, and consequently Ubi-LepRNull mice were not exposed to weight loss." (PMID 30694175, 2019). "To further test this hypothesis, in addition to the HFD-induced T2D model, we examined the effect of Becn1F121A-mediated autophagy hyperactivation in db/db mice, a genetic model of obesity and T2D lacking the functional leptin receptor." (PMID 29898399, 2018).
Obesity (continued). "So our results also confirmed the negative effects of leptin/lepR related obesity on reproduction." (PMID 29728128, 2018). "Moreover, leptin-deficient ob/ob mice and leptin receptor-deficient db/db mice were important for their wide use in obesity-induced T2DM, although leptin or leptin receptor disorder is not a key point in human T2DM (Wang, Chandrasekera & Pippin, 2014)." (PMID 29682407, 2018). "Given that available experimental evidence has shown that FTO modulates leptin receptor localization within neurons to control food intake and adiposity, our finding provides an additional insight into the linkage between FTO, leptin and adiposity, and obesity-related characters." (PMID 29212175, 2017). "Specifically, db/db mice (Jackson Laboratory), a commonly used type 2 diabetes model lacking a functional leptin receptor and consequently developing severe obesity and glucose intolerance, were fed with regular chow diet (Purina 5001) and either regular (Ctrl) or 1% (w/v) RM drinking water." (PMID 26040234, 2015). "However, the present study is the first to investigate the occurrence of genetic changes in LEP and LEPR genes in DTC, which might be a likely link between obesity and thyroid cancer." (PMID 25810718, 2015). "However, ROCK-1 disruption in these neuronal populations only induces mild obesity as compared to the massive obesity observed in mice lacking LEPR in ARC GABAergic neurons." (PMID 26578907, 2015). "The LEP and LEPR SNPs in this study may not be an obesity marker among Malaysians in this population, but were associated with ethnicity." (PMID 24947733, 2014). "Similarly, obesity in BBS has been associated with hyperleptinemia, which occurs due to leptin receptor mislocalization in hypothalamic neurons in the absence of BBS4." (PMID 23554981, 2013). "Therefore, the reversible modulation of insulin, as well as leptin receptor phosphorylation and signaling, holds significant clinical promise, highlighting the potential of PTP1B inhibition to reduce insulin resistance, restore glycemic balance, and target both type 2 diabetes and obesity." (PMID 39941054, 2025). "Therefore, in parallel, LepR in non-hypophysiotropic neurons may be up-regulated to contribute to obesity-induced sympathoexcitation, which is dependent in part on increased leptin levels." (PMID 32538782, 2020). "Indeed, mice lacking the LEPR on NT neurons (Nt-Cre, Leprlox/lox mice) develop only mild obesity." (PMID 28690493, 2017). "HO patients retain the specific expression of POMC/LEPR/MC4R in the PVN, but there are currently no large-scale clinical studies on the treatment of obesity." (PMID 41601974, 2026). "The fact that the hypothalamic expression of the leptin receptor (Lepr), regulated by its own hormone ligand, was not altered due to the CAF diet would be in line with this obesity-induced hormone resistance." (PMID 36837766, 2023). "Here, we show that the natural isothiocyanate and potent NRF2 activator sulforaphane reverses diet-induced obesity through a predominantly, but not exclusively, NRF2-dependent mechanism that requires a functional leptin receptor signaling and hyperleptinemia." (PMID 35323110, 2022). "Systemic leptin receptor blockade attenuates hypertension in NZO mice, but does not exacerbate obesity and SDB." (PMID 34276408, 2021). "The use of mice models lacking LepR in SF1 neurons has demonstrated that these neurons mediate, at least in part, the anti-obesity effect of leptin." (PMID 32069871, 2020). "The lack of the leptin gene leads to a lethal form of obesity development and an alteration in leptin pathway homeostasis, and the abnormally high leptin level observed in obese subjects could result in leptin resistance because of decreased leptin receptor signaling." (PMID 27983705, 2016).
Obesity (continued). "ROS production has been found to increase in the WAT of KKAy mice (a model of non-diabetic obesity), diet-induced obesity (DIO) mice and obese and type 2 diabetic db/db−/− (knock-out for the leptin receptor) mice." (PMID 25257998, 2014). "Although the LepR(+) phenotype is not investigated in skeletal muscle (yet), CD140a(+)/Sca1(−) is likely to be a corresponding subpopulation accompanying fatty degeneration secondary to metabolic ECM changes in patients with diabetes and obesity." (PMID 37463149, 2023). "Thus, obesity-induced changes in CD4+, but not CD8+, T cell production of IFN-γ depends on T cell-specific leptin receptor expression." (PMID 37276236, 2023). "However, clinical (BMI) signs that corroborated with plasma leptin for underweight and obesity exist, and there appear to be no significant polymorphic changes observed in the LEP and LEPR gene." (PMID 35886710, 2022). "There was a significant difference in the number of carriers between the groups of children with and without obesity [p=0.0107 (0.0014-0.0553); median (IQR) of p-values distribution] for the LEPR gene, where 21 VUS and 2 DCVs were identified [BMI SDS=2.8 (0.6); median (IQR)]." (PMID 35574020, 2022). "However, there are no concise reports on the genotypic effect of the leptin receptor gene (LEPR) on fat distribution and obesity-related metabolic abnormalities in a Korean population." (PMID 32517169, 2020). "Here, it has been suggested that LepR is not the main leptin transporter in human BBB, but rather the megalin receptor, since the authors observed a reduction in brain leptin uptake by eliminating the megalin receptor in the endothelial cells of the BBB, which induced hyperphagia and obesity." (PMID 35563589, 2022). "Furthermore, transgenic mice lacking specific proteins expressed in the VMH including leptin receptor, steroidogenic factor 1 (SF-1), melanocortin-4 receptor (MC4R), and brain-derived neurotrophic factor (BDNF), exhibits obesity, hyperphagia, and low locomotor activity similar to AC3−/− mice." (PMID 19750222, 2009). "However, when LEPR was in vivo abrogated in proopiomelanocortin (POMC) neurons of ARCs, which are well-known to foster fullness and satiety responses, mice developed mild obesity, hyperleptinaemia and glucose intolerance without changes in food consumption or EE." (PMID 34208585, 2021).